MIPEPP2 (mitochondrial intermediate peptidase pseudogene 2)
Gene: Processed pseudogene on chromosome 1 (238,777,049 to 238,779,200, reverse strand). Ensembl gene ENSG00000224783.
Diseases named in the same sentence as MIPEPP2 in open-access papers:
MIPEPP2 is named in the same sentence as 1 disease in open-access papers, as found by Europe PMC text mining. Sharing a sentence is not in itself a finding about the gene and the disease. The quoted sentences say what the papers report.
pancreatic cancer (1 paper, 2017). "Previous genome-wide association studies demonstrated that the rs2689154 SNP in MIPEPP2 and the rs12615966 SNP in LOC284998 are associated with the risk of developing pancreatic cancer in Chinese and Japanese populations, respectively." (PMID 28404937, 2017). "Genome-wide association studies (GWAS) have demonstrated that rs2689154 (MIPEPP2), rs4927850 (LOC105374300), rs2255280 (DAB2), rs12615966 (LOC284998), rs7574865 (STAT4), and rs3790844 (NR5A2) SNPs are associated with an increased risk of pancreatic cancer in Japanese and Chinese population." (PMID 28404937, 2017).